INS (insulin)
Diseases named in the same sentence as INS in open-access papers (continued):
Sharing a sentence is not in itself a finding about the gene and the disease.
diabetes (continued). "This form of diabetes generally arises from the concurrent presence of two defects, insulin resistance, which is due to a defect in insulin signaling in target tissues, and a relative defect in pancreatic insulin secretion." (PMID 19007436, 2008). "A 19-year-old Thai primigravida with familial history of diabetes mellitus (DM) was diagnosed as having gestational DM type 2, based on 100 g oral glucose tolerance test, and was poorly controlled with insulin injections." (PMID 18655703, 2008). "Her previous diet-controlled diabetes needed insulin and oral hyperglycaemic therapy to control erratic blood sugars." (PMID 19014625, 2008). "Pluri-potent bone marrow stromal cells (MSCs) provide an attractive opportunity to generate unlimited glucose-responsive insulin-producing cells for the treatment of diabetes." (PMID 18628974, 2008). "Diabetes mellitus is characterized by high levels of blood glucose resulting from defects in insulin production, insulin action or both." (PMID 18716665, 2008). "In people with diabetes mellitus, inadequate insulin secretion results in high blood glucose concentrations." (PMID 18215172, 2008). "At 48 weeks of diabetes, the degree of hyperglycemia is significantly greater than at 12 weeks, with far lower insulin levels." (PMID 18957123, 2008). "Confidence was also reported to be low in commencing intravenous insulin, titrating intravenous insulin, prescribing intravenous fluids and changing diabetes regime." (PMID 18419804, 2008). "When diabetes patients were given an rhIL-6infusion, plasma concentrations of insulin decreased to levels comparable withthat in age and BMI (body mass index)-matched healthy controls, indicating thatthe IL-6 enhanced insulin sensitivity." (PMID 19148295, 2008). "A new treatment plan introduced at a Washington hospital utilised a diabetes team to ensure that new patients consistently received insulin injections." (PMID 18053255, 2007). "The only large trials to investigate treatment focussed on hyperglycemia in MI patients were the Diabetes Insulin-Glucose in Acute Myocardial Infarction (DIGAMI) studies." (PMID 17284309, 2007). "In animal models of obesity and diabetes, soy protein has been shown to reduce serum insulin and insulin resistance." (PMID 17374166, 2007). "Diabetes and hyperglycemia are poor prognostic factors of endometrial cancer, and in vitro insulin responsiveness and enhanced proliferation of endometrial cancer cells have also been reported." (PMID 17233921, 2007). "Analysis of the diabetes data in the INS gene region demonstrates the need for further investigation of these methods." (PMID 17508343, 2007). "A quantitative understanding of the regulation of insulin pulsatility is important to the understanding of glucose metabolic control, and to diabetes research." (PMID 17912360, 2007). "The mouse phenotype described here, characterized by a low level of insulin secretion and a high level of glucosuria, is reminiscent of a monogenic (HNF1α) form of diabetes." (PMID 18074013, 2007). "In reference to insulin metabolism, both 18:0 and TFA fed at high levels (8% en) also induced inflammatory markers that are associated with diabetes." (PMID 17224066, 2007). "Diabetes, a life long progressive disease, is the result of body'sinability to produce insulin or use insulin to its full potential,and is characterized by high circulating glucose." (PMID 17641741, 2007). "Continuous glucose monitoring is now available and is an important advancement in the management of diabetes since patients will have improved their ability to adjust insulin and to better anticipate and therefore prevent hypoglycemia." (PMID 17448241, 2007). "Most patients were treated with oral agents, insulin monotherapy or insulin combination therapy; only 7% controlled their diabetes with diet and exercise alone." (PMID 17967177, 2007).
diabetes (continued). "But already years ago it was shown that PNMT activity was approximately 2-fold higher in the brainstem of streptozotocin-induced diabetic rats than in controls, and the administration of insulin partially prevented the effects of diabetes on PNMT activity." (PMID 17645789, 2007). "In TNDM, patients are younger at the diagnosis of diabetes and have lower initial insulin requirements." (PMID 17349054, 2007). "Excluded from the study were people being treated for their diabetes solely by hospital, who are more likely to be treated on insulin and less likely to be on diet alone." (PMID 17306017, 2007). "Web-based management of diabetes care changed tasks and duties of the diabetes team as the system required extra competency of nurses in insulin dose adjustments." (PMID 18093904, 2007). "Further studies will investigate the molecular basis of stimulation of insulin secretion by L-arginine in surrogate β cells, which will be a useful step in the development of insulin-replacement therapies of diabetes." (PMID 17941991, 2007). "Diabetes control was significantly worse in South Asians, but a smaller proportion of this group were insulin treated." (PMID 17678547, 2007). "Early stages of obesity, type 2 diabetes mellitus, hypertension, and metabolic syndrome X are characterized by insulin resistance restricted to muscle tissue." (PMID 18078524, 2007). "Factors that were significant predictors of total costs for US adults with diabetes in 2003 were insurance status, number of comorbidities, physical health status, and insulin use." (PMID 17442110, 2007). "The discovery of insulin in the 1920's was a major advance in diabetes treatment – freeing patients from the then "state of the art" starvation diets that, at best, prolonged survival for a few weeks, months, or in very rare cases, a few years." (PMID 17201925, 2007). "A larger group of the respondents (73%) were treating their diabetes with oral medication while (21%) and (6%) were treating their diabetes with insulin and lifestyle modification respectively." (PMID 18028552, 2007). "Liver is an insulin dependent tissue, which plays a pivotal role in glucose and lipid homeostasis and is severely affected during diabetes." (PMID 17892543, 2007). "Conversely, it has long been known that chronic insulin therapy for diabetes leads to weight gain and decreased flux of fatty acids compared to isocaloric controls." (PMID 17663761, 2007). "Overall, the more recently diagnosed the diabetes, the more motivated the patients are to initiate insulin injections." (PMID 17727695, 2007). "The United Kingdom Prospective Diabetes Study demonstrated the progressive decline in β-cell function that occurs over time in type 2 diabetes and the eventual need for insulin therapy in most patients." (PMID 17448241, 2007). "Type 1 Diabetes Mellitus results from an autoimmune destruction of the pancreatic beta cells, which produce insulin." (PMID 17941991, 2007). "It is well recognized that intensive treatment can help to delay the onset of diabetes-related complications and that many patients with type 2 diabetes require insulin therapy at some stage to achieve or maintain good glycaemic control." (PMID 18096074, 2007). "This was also found in the logistic regression analysis, thus indicating that the scale has criteria validity, i.e. the subscales of diet and insulin predict "adherence" or diabetes management." (PMID 17625707, 2007). "At follow-up, women with diabetes were older, heavier (higher BMI), shorter, had larger WHR and sum of skinfolds, more insulin resistant and more likely to have a family history of diabetes than either IGT/IFG or NGT women." (PMID 17640759, 2007). "Hypoglycemia (low blood sugar) is a frequent complication of insulin-treated diabetes, affecting patients with type 1 diabetes mellitus in particular." (PMID 17326710, 2007).
diabetes (continued). "The therapeutic hormone insulin is a small protein used daily in the medical treatment of diabetes by millions of people." (PMID 18093308, 2007). "Although the proportion of South Asian patients with good diabetes control is significantly lower in our population, a lower proportion are receiving insulin." (PMID 17678547, 2007). "Type 2 diabetes mellitus patients taking premixed insulin were identified from German clinics and were eligible to switch to glargine plus OADs at the physicians’ and patients’ discretion, as part of routine clinical practice." (PMID 17997807, 2007). "Several animal studies have demonstrated increased collagen production with insulin and increasing the level of insulin administered to mice with diabetes improved all phases of healing." (PMID 17364003, 2007). "The DPP also found a significant reduction in the incidence of diabetes with troglitazone, another insulin sensitiser; however, troglitazone was discontinued before the end of the study owing to concerns regarding liver toxicity." (PMID 17697384, 2007). "Participants also had questions about diabetes that were outside the expertise of the extension educator (e.g., questions about insulin, foot care, and matching insulin to food)." (PMID 17173720, 2007). "When insulin was introduced into clinical practice, it was assumed that it would provide a complete therapy for diabetes mellitus." (PMID 23675048, 2007). "It is estimated that more than 40% of patients with type 2 diabetes mellitus (T2DM) worldwide use premixed insulin as part of their therapeutic regimen." (PMID 17997807, 2007). "CAD was defined as the presence of a 70% stenosis in one major coronary artery, and DM was characterized as a fasting glycemia > 126 mg/dl or known diabetics (personal history of diabetes or previous use of anti-hyperglycemic drugs or insulin)." (PMID 17651487, 2007). "In the DPP, treatment with metformin reduced the incidence of diabetes by 31%, although this effect was less marked in older patients, perhaps owing to age-related differences in insulin secretion." (PMID 17697384, 2007). "Defects in insulin release or its utilization lead to scores of metabolic disorders, including diabetes." (PMID 17912360, 2007). "Recent data have confirmed that whereas mitochondrial numbers are decreased in diabetes and insulin resistant states, thiazolidinedione treatment can result in increased mitochondrial biogenesis in man." (PMID 19936080, 2007). "Normalization of serum glucose level by oral medication or insulin therapy is the basis of every treatment of diabetes related complications." (PMID 17803821, 2007). "Despite being well-accepted by symptomatic diabetes patients, insulin therapy is still often delayed in less severe patients, and is rarely used as an alternative treatment." (PMID 17727695, 2007). "The aim of this study was to analyze the psychometric properties of the insulin management diabetes self-efficacy scale (IMDSES) on type 1 diabetes patients from southern Brazil." (PMID 17625707, 2007). "Taken together, these results indicate a direct role of NO in the impairment of insulin-mediated signal transduction in skeletal muscle, and possibly in the pathogenesis of type 2 diabetes mellitus." (PMID 16729893, 2006). "In order to improve the health of people with Type 1 diabetes in developing countries, a clear analysis of the constraints to insulin access and diabetes care is needed." (PMID 16504123, 2006). "An interesting survey of mathematical models using control for glucose-insulin and management of diabetes is given by Palerm in his Ph." (PMID 16808835, 2006). "The greater the driving distance for adults with diabetes to their source of primary care, the less likely they are to be using insulin." (PMID 16872541, 2006). "These authors forget, though, that insulin levels for intermediate time points (30, 60, 90 minutes) are being challenged by the main entities that deal with diabetes in the world today." (PMID 17119773, 2006).
diabetes (continued). "Among respondents with diagnosed diabetes, 79.4% (or an estimated 69,792 adults) reported using oral glucose-lowering medications, and 24.6% (or an estimated 21,643 adults) reported using insulin." (PMID 16539787, 2006). "The number of individuals with diabetes (glucose ≥126 mg/dL) in the intervention group was reduced by 19%, demonstrating that this therapeutic lifestyle-change program improves insulin sensitivity." (PMID 16356358, 2006). "In contrast, individuals who received a diagnosis of type 2 diabetes and received insulin had significantly higher total diabetes related medical costs than individuals who received an oral antidiabetic agent only." (PMID 16412255, 2006). "During the last decades, a variety of models have been devoted to different aspects of diabetes, including glucose and insulin dynamics, management and complications prevention, cost and cost-effectiveness of strategies and epidemiology of diabetes in general." (PMID 16808835, 2006). "Most patients have type 2 diabetes mellitus (T2DM), characterized by a combination of insulin resistance and progressive loss of insulin secretion." (PMID 16901335, 2006). "The aim of this process is to look at the provision of care for Type 1 diabetes from the viewpoint of the entire health system to see where improvements are necessary to address the problems that hamper access to insulin and care for their diabetes." (PMID 16504123, 2006). "His diabetes was managed with human isophane insulin injections, 18 units in the morning, 6 units in the evening with HbA1c of 8.2% (normal range 5.1%–6.4%)." (PMID 16942396, 2006). "Within the MCQs we also asked for the pathophysiological reasoning (e.g. interpretation of a blood gas analysis in case of decompensated diabetes mellitus type 1 or control after initialisation of an insulin therapy)." (PMID 17032439, 2006). "This type of drug would be beneficial for treating diseases where AKT activity is limited, such as for restoring insulin sensitivity in the context of diabetes mellitus." (PMID 16441841, 2006). "Specifically, individuals who were older, were diagnosed with nephropathy, or were classified with type 2 diabetes based upon a diagnosis of type 2 or diagnosis of type 2 and receipt of insulin had significantly lower diabetes-related prescription drug costs." (PMID 16412255, 2006). "In diabetes research and clinical practice, it is very important to assess β cell function and insulin sensitivity, so as to evaluate the pathological status and risk of an individual." (PMID 16842624, 2006). "For example, individuals with good glycemic control were less likely to treat their diabetes with medication and less likely to be prescribed insulin (either alone or in conjunction with oral antidiabetic drugs)." (PMID 16412255, 2006). "Excluded subjects had a longer duration of diabetes, less use of insulin, greater use of oral hypoglycemic agents and Medicare health insurance, lower BMI, and somewhat lower incomes." (PMID 16872541, 2006). "In order to study such patterns, a clear analysis of the constraints to insulin access and diabetes care is needed." (PMID 16504123, 2006). "Insulin or oral hypoglycemic agents were prescribed among 88% of participants with diabetes mellitus." (PMID 17005050, 2006). "In this type of diabetes, the insulin producing beta cells of the pancreas have been destroyed and thus are unable to make insulin." (PMID 16556307, 2006). "Because of its effect on insulin, carbohydrate restriction is one of the obvious dietary choices for weight reduction and diabetes." (PMID 16790045, 2006). "A prospective case based therapeutic comparison between insulin, sulfonylurea, metformin and thiazolidinedione was observed over one decade with 20 CFRD patients diagnosed using American Diabetes Association guideline standards." (PMID 16790062, 2006).
diabetes (continued). "In their majority, these reviews concentrated on specific aspects of diabetes such as glucose-insulin dynamics, computer algorithms and devices, sensors and control, mathematical and software aspects, glycemic index, burden and cost of diabetes." (PMID 16808835, 2006). "As would be expected, individuals with type 1 diabetes, followed by those with type 2 diabetes on insulin, had the highest expenditures for diabetes testing supplies." (PMID 17164006, 2006). "Impaired β-cell function predicts future diabetes, and work from our laboratory and others suggest that the ability of pancreatic β-cell to compensate for prevailing insulin sensitivity is highly heritable." (PMID 16869959, 2006). "By contrast, individuals with poor levels of glycemic control were significantly more likely to treat their diabetes with insulin." (PMID 16412255, 2006). "Both increased insulin secretion and insulin resistance result from obesity, and hyperglycemia and insulin resistance are the hallmarks of diabetes." (PMID 16999863, 2006). "This study was undertaken to investigation the effect of Diasulin, a poly herbal drug composed of ethanolic extract of ten medicinal plants on blood glucose, plasma insulin, tissue lipid profile, and lipidperoxidation in alloxan induced diabetes." (PMID 15969768, 2005). "These students face the daily task of balancing food intake, physical activity, and medication — usually insulin — to survive with diabetes." (PMID 16263044, 2005). "Because carbohydrate is the major secretagogue of insulin, some form of carbohydrate restriction is a prima facie candidate for dietary control of diabetes." (PMID 16018812, 2005). "We were also interested in exploring the interaction with diabetes mellitus as insulin resistance can lead to increased levels of plasma insulin, lower levels of plasma sex hormone binding globulin and, consequently, increased levels of free estrogen." (PMID 16280037, 2005). "As expected, diabetes affected the kidney function, although only in insulin-dependent women, of whom about half had type II diabetes." (PMID 16263522, 2005). "The WDPCP also frequently receives requests from school professionals for information on new equipment, such as insulin pens and pumps, and for information on new diabetes medications being used by their students." (PMID 16263044, 2005). "We propose that insulin and IGF-I therapy, partially working through TRPV1, can improve complications associated with diabetes mellitus." (PMID 15857517, 2005). "Diets containing carbohydrates with a high glycemic index have been associated with high fasting glucose and insulin levels, increased risk of impaired glucose tolerance (IGT) and increased IGT rates that developed to diabetes." (PMID 16021275, 2005). "In subjects with diabetes, the insulin sensitizer rosiglitazone (RSG), a drug also known to improve vascular function, was administered for 3 months to see how it altered these relationships." (PMID 15790404, 2005). "Additional studies to test the impact of transplanted IPCs in animal models of diabetes therefore await production of IPCs capable of insulin secretion at levels higher than achieved here." (PMID 15839736, 2005). "These patients develop diabetes when tissues of the body fail to utilize glucose appropriately owing to increased resistance to insulin and concomitant beta-cell dysfunction of the pancreas." (PMID 15736996, 2005). "T2DM, which accounts for 90–95% of all diabetes mellitus, is a common metabolic disorder, characterized by a combination of IR and insulin secretory defects, occurring in varying proportions." (PMID 16095537, 2005). "Those who were uninsured, had diabetes for a longer period of time, used insulin or multiple oral agents, or had high cholesterol had poorer glycemic control." (PMID 15833140, 2005).